IFNG (interferon gamma)
Diseases named in the same sentence as IFNG in open-access papers (continued):
Sharing a sentence is not in itself a finding about the gene and the disease.
tumor (continued). "To test this hypothesis, we measured the amount of TNFα produced by IFNγ-primed macrophages in response to antibody-coated tumor cells in presence or absence of PtdIns 3-kinase/Akt inhibitor." (PMID 19148288, 2009). "Thus synergistic increase in TNFα production upon co-stimulation with IFNγ and antibody-coated tumor cells was not surprising." (PMID 19148288, 2009). "A significant increase in the number of IFNγ-producing cells was observed in the group of LM-LLO-Mage-b/2nd compared with the control groups, demonstrating that LM-LLO-Mage-b/2nd was able to induce Mage-b-specific immune responses even in mice with 4T1 tumours." (PMID 18728665, 2008). "In addition to its role in immune cells, IFNγ inhibits the growth of a number of nonhematopoietic cell types, including several tumor types." (PMID 17697357, 2007). "The reduction of tumour incidence was ablated in mice that lacked interferon gamma." (PMID 17565340, 2007). "Several cytokines--interleukin 2 (IL-2), tumour necrosis factor alpha (TNF-alpha) and interferon gamma (IFN-gamma)--and prostaglandin E2 (PGE2) known to modulate tumour growth and metastasis were examined to determine whether they regulate nm23 expression in JAR in vitro." (PMID 8080727, 1994). "Because even pharmacological short-term inhibition of glycolysis- and OGT-activity influenced IFNγ production and STAT1 phosphorylation, we propose that this mechanism equips Th1 cells to adapt dynamically to their environment; this could have important consequences for anti-tumor immunity." (PMID 41184108, 2026). "Notably, after treatment, proinflammatory cytokine secretion was significantly increased by tumor‐border, but not by non‐tumor lung tissue slices, compared with the medium control, evidenced by higher levels of IFNγ (1.7‐fold), IL‐2 (1.4‐fold), and Perforin (1.5‐fold)." (PMID 40952312, 2025). "IFNγ pathway mutations were found at similar frequencies compared to antigen presentation mutations such as in B2M, TAP, or HLA molecules, suggesting that the pressure induced by T cells is not potent enough in most tumours to select for these types of mutations." (PMID 39746898, 2025). "KCL-HO-1i also resulted in an increased proportion of CD8+ T-cells capable of expressing IFNγ within the TME, an effect that was further boosted when KCL-HO-1i was administered alongside 5-FU or gemcitabine, where CD8+ T-cells could be found infiltrating the tumor." (PMID 40768602, 2025). "A patient with a TIL-high, PD-L1-positive, interferon-gamma-rich tumor may proceed directly to combination checkpoint blockade, whereas a patient with a non-inflamed tumor might first receive an oncolytic virus or an epigenetic modifier such as an HDAC inhibitor to prime the tumor for immunotherapy." (PMID 40643516, 2025). "Excessive acetylcholine suppresses interferon-gamma (IFNγ) production by CD8+ T cells and promotes T cell differentiation toward the Th2 phenotype.Furthermore, in terms of metabolic reprogramming, nerve cells may provide an alternative nutrient source to sustain tumor growth." (PMID 40861469, 2025). "Such a cytokine window is hypothesized to facilitate dosing for maximum killing potency within a range focused on safety (little to no IFNγ release) to that focused on IFNγ’s anti-tumor properties, which can be modulated at both an inter-patient and intra-patient basis depending on tolerability." (PMID 38455046, 2024). "Given that IFNγ activates ZEB1, future studies are motivated to address if the metastatic potential of UM is triggered by such soluble inflammatory factors or if a single critical factor could independently trigger an unique intrinsic signaling pathway downstream of 4-1BBL expressed on tumor cells." (PMID 38191418, 2024). "Furthermore, in IFNγ ko mice, PC therapy failed to reduce intracranial tumor burden." (PMID 39551601, 2024).
tumor (continued). "Future studies will focus on understanding whether T-cell activation and subsequent IFNγ signaling are major drivers of increased MHCI and MHCII on tumor cells in vivo, and whether cells other than T cells, such as neutrophils, are required for tumor stasis in response to EZH2 inhibitor." (PMID 38265267, 2024). "Moreover, IFNG and Merck18, which can reflect the ability to release IFN-γ, showed that patients with low CRRGPI scores could release more IFN-γ, which indicated a stronger ability to kill the tumour (P < 0.001)." (PMID 38556542, 2024). "In addition, higher initial 89Zr-anti-IFNγ uptake was significantly predictive of response to tumor vaccination and could be used to stratify responders and non-responders." (PMID 39104861, 2024). "Therefore, in immunodynamics, (TGFβ)(pSTAT3) represents negative immune power, and (IFNγ)(pSTAT1) represents positive immune power; conversely, in tumor ecodynamics, (TGFβ)(pSTAT3) represents positive tumor ecological power, and (IFNγ)(pSTAT1) represents negative tumor ecological power." (PMID 38807760, 2024). "In an independent study, eliminating CD4+ T cells or NK1.1+ NK cells individually did not impair tumor response to DCP-IL-12/FLT3L treatment, and disrupting CD4+ T cells was associated with compensatory increases in both total and activated (IFNγ+ or GZMB+) CD8+ T cells." (PMID 37996514, 2024). "Thus, the effect of IFNγ on tumor cell response to CAR-T therapy will not only depend on context and timing but also the ability of tumors cells to induce inhibitory receptors like HLA-E in response to inflammatory signals, as well as their general sensitivity to IFNγ-mediated death." (PMID 38052854, 2023). "Moreover, tumours derived from cells chronically treated with IFNγ prior to implantation in syngeneic mice are resistant to ICBT9; while in vivo CRISPR screens revealed IFNγ signalling as a driver of ICBT resistance in multiple syngeneic mouse tumour implantation models." (PMID 37752135, 2023). "Tumour antigen-reactive TILs contained features of mouse TEX and were enriched for gene signatures associated with tissue residency (CD103, HOBIT), effector function (GZMB, IFNG), negative feedback (HAVCR2, ENDTP1 (CD39)), and transcriptional control of exhaustion (TOX, BLIMP1)." (PMID 37386922, 2023). "6SA reduces tumor volume without diminishing the number of TILs by inducing caspase-8 mediated cell apoptosis, and also concurrently augmenting the secretion of interferon-gamma (IFN-γ) and tumor necrosis factor-alpha (TNF-α), and improves the immune microenvironment of TNBC." (PMID 37660039, 2023). "Hence, we hypothesise that alterations triggered in tumour cells by the miRNAs may lead to more efficient and faster CTL‐mediated induction of target cell death, a quicker T cell detachment, and possibly even lower levels of IFNγ secretion." (PMID 36718025, 2023). "In addition, lenvatinib reactivates interferon-gamma signaling in tumor cells by inhibiting fibroblast growth factor receptor (FGFR) and enhances its combined antitumor activity with anti-PD-1 antibodies by blocking FGFR4 to reduce tumor PD-L1 levels and Treg differentiation." (PMID 37916160, 2023). "Moreover, tumor cells remained suppressed after re-inoculation of mice with tumor cells, suggesting that CPI-444 induces systemic antineoplastic immune memory and that the combination of CPI-444 with CTLA-4 mAb increases the presence of CD8+T cells and IFNγ and Gzm B levels in tumors." (PMID 36159861, 2022). "Therefore, we further programmed our improved AND–NOT tumor-targeting circuit toward induction of IFNγ, whose intratumoral production/function may mimic such a protective axis." (PMID 35304449, 2022). "Notably, hypoxic tumor MVs exhibited more significant effects on the decrease of IFNγ production by NK cells compared to normoxic MVs, and decreased cytotoxicity of exosome-treated NK-92/NKD cells was found to be directly correlated with the reduced expression of IFNγ by these cells." (PMID 35031075, 2022).
tumor (continued). "Thus, the enrichment of JAK1 truncating frameshift mutations in dMMR/MSI EC at least partly explains their lack of IFNγ response, and may also partly explain the absence of a prognostic benefit of MMR loss in this tumour type." (PMID 35262923, 2022). "Furthermore, this effect was not restricted to murine cells as stable expression of the inhibitory biologic in human tumour cells (A375 and A549) also resulted in the same phenotype, which in turn potentiated the cells to boost the surface levels of MHC-I in response to IFNγ." (PMID 35982220, 2022). "As we used cocultures of OAV infected GBM cells and HLA-A/B matched PBMCs (to mimic the situation in the tumor area) to determine the IFNγ release, we could not discriminate whether the IFNγ we measured originated from the OAV infected GBM cells or from the cocultured PBMCs or from both." (PMID 36077380, 2022). "We then discussed the effects of other cell types on epithelial cells in tumor tissue, and the results indicated that immune cells could regulate epithelial cells through specific ligand–receptor pairs, such as TNFSF14-TNFRSF14, MIF-(CD74+CD44), IFNG-(FINGR1+IFNGR2), CXCL12-ACKR3, and CXCL11-ACKR3." (PMID 36569924, 2022). "Indeed, the tumor nodules were characterized by diminished levels of inflammatory cytokines IFNγ and TNFα when compared to non-tumoral tissue, while the intratumoral frequency of Treg was enhanced, which is classically associated with HCC progression and poor survival." (PMID 34638465, 2021). "To investigate whether iTreg are tumor-reactive, we also performed single-cell sequencing of sorted MAMI-specific Treg and Tconv from autologous blood using either mam34–48-labeled HLA Class II tetramers or the IFNγ-secretion assay targeting MAMI-reactive IFNγ+Teff." (PMID 33602930, 2021). "However, co-inoculation of normal BMSCs or BMSCs pretreated with IL-17 or IFNγ individually did not increase the numbers of macrophages and monocytes in the tumor microenvironment, and the BMSC induced slight increase of MDSCs was not statistically significant." (PMID 33889575, 2021). "Finally, the existence of a “paradoxical” subgroup of CRC (34% of CRCs) was identified that does not display an IFNγ response despite the secretion of mature IL-18 by tumor cells and that features downregulated IL-17, chemokines, and antimicrobial agent gene signatures." (PMID 33430344, 2021). "In addition, neither T317 in food nor D-Nap-GFFY had effect on tumor growth/weight in IFNγ-/- mice." (PMID 33456564, 2021). "Thus, our results suggest that immunotherapeutic approaches should aim to augment TNFα rather than IFNγ in the tumor microenvironment, and that MSCs may be a barrier to stimulating effector cells within the tumor microenvironment." (PMID 34869307, 2021). "IFNγ produced by converted Treg cells and CD8 T cells after αPD1 + αGITR combination therapy may also have an additional effect of driving the reprogramming of subsequent waves of tumor Treg cells, as suggested by observations made in the context of Helios−/−, NRP1−/−, and/or CARMA−/− Treg cells." (PMID 33976133, 2021). "In addition, IFNG releases from CD8 + T cells could downregulate two subunits of glutamate-cystine antiporter system xc-, restrain tumor cell cystine uptake, and finally promote tumor cell lipid peroxidation and ferroptosis." (PMID 34222241, 2021). "However, IFNγ produced by effector CD8+ T cells downregulates SLC7A11 and SLC3A2 by reducing the release of cysteine and GSH from CAFs, thereby inhibiting cystine uptake in cancer cells, resulting in the induction of tumor lipid peroxidation and ferroptotic cell death." (PMID 34796174, 2021). "Based on the scRNAseq results correlating OPN expression with IFNγ signaling pathways, we hypothesized that OPN may contribute to ‘adaptive immune resistance’ as PD-L1, in which tumor-immune interactions induce a counterregulatory program that protects tumor cells from immune clearance." (PMID 33670921, 2021).
tumor (continued). "Furthermore, polarized secretion could still induce signal spreading as the immunological synapse does not spatially restrict IFNγ secretion by CTLs, allowing IFNγ bystander activity important to alter tumor environment." (PMID 33195256, 2020). "Importantly, the enrichment of interferon-gamma (IFN-γ) and tumor necrosis factor (TNF)-related apoptosis-inducing ligand (TRAIL) pathways may reflect the host immune responses towards the presence of the tumor." (PMID 32575471, 2020). "Furthermore, antibody-mediated depletion of TGF-βi led to reduced tumour burden in spontaneously developing murine models of PDAC and critically, these tumours were more highly infiltrated with CD8+ T cells that expressed greater levels of granzyme B, IFNγ and TNFα." (PMID 32967079, 2020). "Moreover, ILC2 might give rise to IFNγ-producing ILC1s and the potential for transdifferentiation into other ILC types, introducing increasing levels of complexity in the study of ILC2s’ role during tumor progression." (PMID 33138017, 2020). "Indeed, adoptive transfer of tumor-specific CD8+ T cells primed ex vivo in the presence of IL-12 resulted in enhanced antitumor responses, increased persistence of infused T cells, as well as increased expression of IL-2Rα (CD25], ICOS, OX40, granzyme B, and IFNγ." (PMID 33178203, 2020). "Hence, it is likely that using therapeutic strategies fostering the accumulation of non-dysfunctional IFNγ-secreting T cells within the tumor could dramatically improve the efficacy of ICPi therapy." (PMID 32707692, 2020). "Also, treatment of CXCL9 could dose-dependently reduced the mRNA expression and secretion of anti-tumour cytokines from CD8+ cytotoxic T cells, including TNFα, IL2, and IFNγ, further proving that CXCL9 treatment could lead to cytotoxic T cell exhaustion and dysfunction." (PMID 31913856, 2020). "Interestingly, the C4 with high-expression FAM111A expression group was also related to the MHCs and immunostimulators, which might indicate the activation of the interferon gamma response pathway and a more complex relationship between FAM111A and tumor immunity in LGGs." (PMID 33194678, 2020). "In addition, TLR-L and/or Zol-treated pDCs elicited production of IFNγ and TNFα in cocultures and stimulated the cytotoxic activity of γδ T cells as illustrated by the upregulation of CD107 surface expression and secretion of perforin following culture with tumor cells." (PMID 32435249, 2020). "However, in this context neutrophil infiltration induced anti-tumor effects since IL-17 potentiated the direct killing capability of neutrophils by enhancing the production of cytotoxic molecules, including reactive oxygen species (ROS), MPO, TNF-related apoptosis-inducing ligand (TRAIL), and IFNγ." (PMID 33262763, 2020). "Our results suggest that pMSCs might enhance the anti-tumor activities of NK cells through IL1ra or via other mediators including IL12, IL-18, and IFNγ receptors and their corresponding cytokines (IL-18, IL-12, and IFNγ), which are known to be involved in the anti-tumor activity of NK cells." (PMID 30728068, 2019). "However, gemcitabine alone or IFNγ alone did not significantly inhibit tumor growth in vivo." (PMID 30782607, 2019). "A phase II trial has recently evaluated IFNγ-DC-derived exosomes loaded with MHC I/II confined cancer antigens as maintenance immunotherapy after chemotherapy in advanced patients without tumor progression, and exosomes may be used as anticancer vaccines in the future." (PMID 31360701, 2019). "Since Chi3l1 deficiency reduced IL-4 production in Th2 cells while increasing IFNγ expression in Th1 and CD8 T cells, targeting Chi3l1 could provide prominent anti-tumor effect by driving Th1 response while suppressing the activity of tumor-promoting Th2 cells." (PMID 29403003, 2018).
tumor (continued). "To elucidate whether tumor neo-epitopes provided a basis for tumor immune recognition, we stimulated CD8+ peripheral blood lymphocytes (PBLs) with pools of predicted peptides for 12 days in vitro, followed by rechallenge with the same peptides and analysis by IFNγ ELISpot." (PMID 29545564, 2018). "Selumetinib, whether as monotherapy or in combination with anti-CLTA-4, did not change the percentage of IFNγ-producing T-cells within total splenocytes and tumor samples, following ex-vivo stimulation with anti-CD3, when compared to control or anti-CTLA-4 antibody alone (data not shown)." (PMID 28807001, 2017). "Thus, HLA-DR may be a marker of IFNγ activity in the microenvironment of some (but not all) tumours." (PMID 26822383, 2016). "Furthermore, when isolated from the tumor environment, such leukocytes attacked tumor cells in vitro for at least 48h in culture, even without in vitro exposure to CpG and/or IFNγ (image 1 vs 2 ***p < 0.0001), suggesting some degree of prior in vivo activation even in the absence of treatment." (PMID 27341020, 2016). "Furthermore, while tumor-bearing animals treated with control antibody did have elevated IFNγ levels compared with nontumor-bearing animals, the levels of IFNγ were 20-fold lower than levels observed in animals that had tumor regressions following combination treatment." (PMID 27169467, 2016). "In the present study, CY+TLRa treatment in vivo followed by IFNγ and TLRa reexposure in vitro generated what appears to be a maximum tumoricidal state in Gr1dim (monocytic) myeloid cells, effectively obliterating actively dividing, non-irradiated tumor cells for at least seven days in culture." (PMID 27341020, 2016). "The tumor-specific CD8+ T cells may kill tumors independent of IFNγ, possibly via perforin pathway." (PMID 24872958, 2014). "Therefore, various therapeutic applications to enhance tumor immunity have been attempted, including anti-TGFβ antibodies, anti-CCR4 antibodies, anti-CTLA4 or Programmed Death-1 (PD-1) inhibitory molecules, TLR7 or Bacillus Calmette-Guerin (BCG) boosting therapy, and IL-2 or IFNγ treatment." (PMID 23667623, 2013). "We have hypothesised that DNMTi can also act through the activation of the IFNγ-signalling pathway components and we therefore focused on the expression levels of the selected genes from this pathway, namely interferon responsible factors 1 (IRF-1) and 8 (IRF-8) and STAT-1 in tumour cells." (PMID 22015556, 2011). "Consequently, tumor cells did not induce secretion of IFNγ by iNKT cells." (PMID 20593019, 2010). "Whether the IFNγ blockade is mediated by tumor-derived soluble factors is currently not known." (PMID 20593019, 2010). "Interestingly, we also observed correlations between pathways (IL12, IFNG, IL2) involved in Th1 mediated immune response, as well as correlations between pathways (IL13, TGFB) that act via Th2 immune responses to putatively suppress the tumor inhibitory role of Th1 pathways." (PMID 21050467, 2010). "The time course of IDO expression in CNE2 cells treated with IFNγ indicated that, once IDO protein was synthesized, it degraded slowly (>72 h), which could result in a long-lasting effect of IDO in NPC patients, resulting in severe tryptophan deprivation and Kyn accumulation at tumor sites." (PMID 19948041, 2009). "This may be because immune responses uncovered by Treg depletion mediate tumour rejection through production of IFNγ and/or that immune responses uncovered by Treg depletion cannot compensate for the lack of IFNγ, which is critical for tumour control even in the absence of Tregs." (PMID 17565340, 2007). "Multiplex immunofluorescence staining of tumor sections from the Dtx2‐overexpressing group not treated with reparixin revealed that CD8+ T cells, especially IFNγ+ CD8+ T cells, were located mainly at the tumor margins (white arrow point)." (PMID 39733452, 2025).